CX3CR1 (C-X3-C motif chemokine receptor 1)
Diseases named in the same sentence as CX3CR1 in open-access papers (continued):
Sharing a sentence is not in itself a finding about the gene and the disease.
Sepsis (continued). "ROC curve analysis highlighted four genes with AUC >0.8 (CX3CR1 = 0.982), suggesting CX3CR1 as a precise sepsis biomarker." (PMID 41332909, 2025). "We categorized the sepsis dataset by patient survival outcomes and examined the mRNA expression levels of the genes CX3CR1, PID1, and PTGDS." (PMID 39763654, 2024). "This study identified three molecular signatures (CX3CR1, PID1 and PTGDS) linked to the diagnosis and poor prognosis of sepsis and ARDS, validated by RT-qPCR and H&E staining in both patient and mouse samples." (PMID 39763654, 2024). "We further explored the diagnostic ability of CD160, CX3CR1, DENND2D and FAM43A for sepsis in both training cohort and test cohort." (PMID 38263335, 2024). "To further validate the diagnostic capability of the four genes CD160, CX3CR1, DENND2D, and FAM43A in clinical samples, we collected the 10 pairs clinical samples from the healthy and sepsis samples." (PMID 38263335, 2024). "In the cecal ligation and puncture (CLP)-induced sepsis model, the number of CX3CR1+CCR2-CD64+CRMs begins to decrease from the first day of sepsis, which is associated with TNF-α and IL-6 signaling and leukocyte infiltration." (PMID 38027963, 2023). "In the end, we managed to formulate a signature of 7 IRGs for the prognosis of sepsis patients: − 0.465 × CCL5 + 0.215 × DEFA4 − 1.487 × NFYC + 1.055 × ESR1 − 0.737 × TNFRSF8 − 0.228 × CX3CR1 + 1.003 × SERPINA3." (PMID 36650470, 2023). "The CX3CR1-dependent adhesion mechanism protects against kidney damage during sepsis, via Ly6Chigh monocytes." (PMID 38299151, 2023). "It was previously reported that the CX3CR1 receptor is functionally important during sepsis, where CX3CR1+ macrophages play critical roles in dead cell/pathogen clearance, maintenance of immune surveillance and barrier function." (PMID 37953266, 2023). "Recent publications demonstrate a role for CX3CR1+ myeloid cells in radio-contrast-agent and sepsis-induced kidney damage." (PMID 34009468, 2021). "A decrease in the expression of MHC-II and CX3CR1 has been described and asscociated with defective Mo activation and sepsis severity." (PMID 32425929, 2020). "Further work performed in this study has revealed that the reduction in CX3CR1 expression is due to endocytosis in line with previous reports on macrophages in sepsis patients." (PMID 30150990, 2018). "A recent study shows that CX3CR1 plays a major, possibly more important, role in the mobilization of monocytes during polymicrobial sepsis." (PMID 29218051, 2017). "Cx3cr1 was reported to be one of the genes most differentially expressed between survivors and non-survivors in two independent cohorts of septic patients and was proposed as a marker of sepsis-induced immunosuppression." (PMID 41532069, 2026). "Emerging evidence highlights that the diverse expression patterns of CX3CR1 within distinct immune cell subsets determine its dual pro-inflammatory and anti-inflammatory effects, and CX3CR1 expression level is closely correlated with patient survival in sepsis." (PMID 41965341, 2026). "In addition, targeted modulation of CX3CR1 in specific immune cell types has shown promising efficacy in preclinical sepsis models." (PMID 41965341, 2026). "Finally, the CDK1/CX3CR1 ratio can be used in combination with lactate levels for prognostic and predictive enrichment in sepsis patients." (PMID 39830374, 2024). "Our study additionally corroborates CX3CR1’s protective function in sepsis." (PMID 38263335, 2024). "The ROC curve results displayed that the AUCs of CD160, CX3CR1, DENND2D and FAM43A were 0.965, 0.986, 0.991 and 0.985 in the training cohort, and 0.773, 0.756, 0.660 and 0.721 in the test cohort, indicating a favorable diagnostic ability for sepsis." (PMID 38263335, 2024). "In addition, multicolor flow cytometry revealed alterations in the composition of circulating monocyte subsets and their downregulation of HLA-DR and CX3CR1 surface expression in sepsis." (PMID 31906585, 2020).
Sepsis (continued). "We could also observe a slightly decreased expression of CX3CR1 on monocytes from patients with sepsis." (PMID 31906585, 2020). "This provides a link between decreased CX3CR1 and immune dysfunction after sepsis." (PMID 27364780, 2016). "Chemokine (C-X3-C motif) receptor 1 (CX3CR1) was identified as the most differentially expressed gene between survivors and non-survivors in two independent cohorts of septic shock patients and was proposed as a marker of sepsis-induced immunosuppression." (PMID 27364780, 2016). "Interestingly, besides sepsis, decreased CX3CR1 mRNA expression was also described in sterile inflammation, such as major vascular surgery." (PMID 27364780, 2016). "This provides a link between decreased CX3CR1 and immune dysfunction after sepsis and suggests that the measure of such a host response messenger RNA (mRNA) marker may be useful in evaluation of injury-induced immune alterations." (PMID 27364780, 2016). "In addition, a study on human sepsis reported that CX3CR1 protein expression was decreased on patients' monocytes." (PMID 23098236, 2012). "During sepsis caused by cecal ligation and puncture (CLP)-induced polymicrobial sepsis animal model, inflammatory monocytes migrated from the bone marrow, approached renal cortical endothelial cells and stimulated monocytes within few hours by increasing CX3CR1-related adhesion." (PMID 40508161, 2025). "Additionally, TLR4-dependent internalization of CX3CR1 may exacerbate sepsis-induced immunoparalysis." (PMID 38245687, 2024). "We selected four MAAGs—CD160, CX3CR1, DENND2D, and FAM43A—to construct a prognostic model for sepsis." (PMID 38263335, 2024). "In this study, differential gene analysis, WGCNA, and machine learning were utilized to identify novel gene signatures related to sepsis and ARDS (CX3CR1, PID1, and PTGDS)." (PMID 39763654, 2024). "Correlation analysis of immune cells revealed that CX3CR1 expression in sepsis and ARDS patients was positively correlated with NK cell and monocyte infiltration, possibly indicating that CX3CR1 recruits these cells to inflamed tissues." (PMID 39763654, 2024). "Combining the findings from both algorithms and WGCNA, three shared biomarkers (CX3CR1, PID1 and PTGDS) were discovered for both the sepsis and ARDS groups." (PMID 39763654, 2024). "The qRT-PCR results exhibited that the mRNA expression of CD160, CX3CR1, DENND2D and FAM43A were obviously down-regulated in the sepsis group which was consisted with previous results." (PMID 38263335, 2024). "This research is unique due to the combination of various machine learning techniques, which systematically identifying three hub genes (CX3CR1, PID1 and PTGDS) as possible biomarkers for diagnosing and predicting outcomes in sepsis and ARDS." (PMID 39763654, 2024). "Expression of the fractalkine receptor (CX3CR1) on monocyte subtypes was also decreased, as has been described for monocytes in sepsis." (PMID 31906585, 2020). "To examine any correlation between HSCs and hUCB-MSCs in the liver during LPS-induced sepsis, we performed two-photon intravital imaging 30 h after hUCB-MSC administration in CX3CR1-GFP+/− mice with LPS treatment for 6 h." (PMID 32014040, 2020). "Circulating monocytes with high levels of CX3CR1 (frataxylin), are present in systemic disease, such as sepsis or HIV infection, while the macrophage subset that invades tissues during acute localized inflammation expresses lower levels of CX3CR1." (PMID 22194858, 2011). "CX3CR1’s interaction with its ligand, CX3CL1, has been acknowledged since 2008, where it was shown to facilitate the arrest and migration of pro-inflammatory cells during sepsis progression." (PMID 38263335, 2024). "Differentially expressed genes between 28-day survivors and non-survivors include transcripts previously linked to sepsis outcomes such as IL1R2, OLAH, and CX3CR1 6,41." (PMID 38890515, 2024).
Sepsis (continued). "Among these 7 IRGs, which could predict the prognosis of sepsis patients, CCL5, DEFA4, ESR1 and CX3CR1 were broadly researched in previous studies." (PMID 36650470, 2023). "During acute kidney injury in polymicrobial sepsis, a combination of murine and human studies demonstrated worse outcome in mice lacking CX3CR1." (PMID 34009468, 2021). "Both flow cytometry and microscopy analyses revealed that during the recovery phase of sepsis, inflammatory Mo with altered expression of cell activation markers, such as MHC class II, CX3CR1 and CD64, invaded the lungs (and probably the kidneys and liver) but remained fully intravascular." (PMID 32425929, 2020). "The immunoreactivity of both molecules was tested on lung samples obtained from 8 non-sepsis control cases and 9 sepsis cases: both CCR2+ and CX3CR1+ mononuclear cells were significantly higher in the sepsis group compared to controls (p < 0.01)." (PMID 33092081, 2020). "Finally, our data may also help in proposing further research into therapies employing CX3CR1 antagonists (AZD8797) or humanised monoclonal antibody of IL-17A (ixekizumab) as potential therapeutic targets in sepsis." (PMID 40433376, 2025). "Unlike FAM43A, ample research exists on CX3CR1’s role in sepsis." (PMID 38263335, 2024). "While there was no significant modification of CX3CR1 and CD16 expression, we found a trend for an enhanced expression of the early activation marker CD69 in vivo after sepsis." (PMID 23098236, 2012).
Cognitive impairment (39 papers, 2012 to 2025). Abnormal cognition is characterized by deficits in thinking, reasoning, or remembering. "Herein, we demonstrated that CX3CR1 deficiency notably attenuated the neuroinflammation and improved neurological recovery, suggesting that the cognitive impairment caused by the HH exposure was more biased toward acute brain injury." (PMID 37234914, 2023). "In this study, we found reduced NK cell cytotoxicity and expansion in a unique subset of CX3CR1+TBX21+ NK cells associated with cognitive impairment in AD patients." (PMID 36405736, 2022). "Reducing microglial reactivity with: (i) partial knockdown of fractalkine receptor CX3CR1; (ii) minocycline treatment, or (iii) annexin-V treatment prevented obesity-associated cognitive impairment." (PMID 34353376, 2021). "We have previously shown that Cx3cr1 deficiency exacerbated tau pathology and led to cognitive impairment." (PMID 30253780, 2018). "Since microglia located in the hippocampus are important for the regulation of adult neurogenesis, chemokine CX3CR1 deficient mice perform adult hippocampal neurogenesis deficit and cognitive impairment." (PMID 28183352, 2017). "Our previous study suggested that enhancement of microglia-specific neuroinflammation via genetic deficiency of Cx3cr1 resulted in accelerated tau pathology and cognitive impairment in an hTau mouse model of tauopathy." (PMID 27974048, 2016). "CX3CR1, which ranked 132, is a key microglial pathway in protecting against AD-related cognitive deficits that are associated with aberrant microglial activation and elevated inflammatory cytokines." (PMID 24917541, 2014). "In accordance, another study further found that CX3CR1-deficient mice display significant cognitive impairment." (PMID 25191897, 2014). "CX3CR1, the fractalkine receptor, is a key member of the microglial pathway that protects against AD-related cognitive deficits that are associated with aberrant microglial activation and elevated inflammatory cytokines." (PMID 22655214, 2012). "Deletion of CX3CR1 or depression of the CX3CL1/CX3CR1 axis reduces Aβ deposition but exacerbates tau pathology, such as increased phosphorylation and aggregation of tau, and this is associated with worsened behavioral and cognitive impairments." (PMID 37452321, 2023). "Moreover, significantly decreased spontaneous alternations in 5xFAD;Cx3cr1−/− mice as compared to 5xFAD;Cx3cr1+/+ cohorts demonstrated that Cx3cr1 deficiency aggravates cognitive impairment in AD." (PMID 35764973, 2022). "The deficiency of CX3CL1 or CX3CR1 in AD models reduces β-amyloid deposition but increases tau phosphorylation and aggregation, with a consequent detrimental effect on the behavioral and cognitive deficit." (PMID 36092814, 2022). "Ablation of microglial C-X3-C motif chemokine receptor 1 (CX3CR1) in mice resulted in phenotypes associated with autism spectrum disorders including cognitive impairment, social withdrawal and resistance to chronic psychological stress-induced anhedonia- and anxiety-like phenotype." (PMID 34211370, 2021). "However, CX3CR1 deficiency was associated with aberrant microglial activation and AD-related cognitive deficits." (PMID 28912710, 2017). "We previously demonstrated that the microglial activation induces tau hyperphosphorylation and cognitive impairment via activation of p38 mitogen-activated protein kinase (p38 MAPK) in the hTau mouse model of tauopathy that was deficient for microglial fractalkine receptor CX3CR1." (PMID 27974048, 2016). "Notably, CX3CR1 deficiency also accelerated tau phosphorylation, aggregation, neuroinflammation as well as cognitive impairment in an hTau mouse model of tauopathy." (PMID 26089772, 2015). "Interestingly, Cx3cr1 deficiency results in heighted accumulation of neurotoxic, oligomeric Aβ, along with severe neuritic dystrophy, preferential loss of post-synaptic densities, exacerbated tau pathology, neuronal loss and cognitive impairment." (PMID 35764973, 2022).
Cognitive impairment (continued). "Notably, a previous study from our group has suggested that deficiency of CX3CR1 in the hTau mouse model of tauopathy resulted in accelerated tau pathology and cognitive impairment, which is mediated via IL-1β-p38 mitogen activated protein kinase (p38 MAPK) signaling pathway." (PMID 26089772, 2015). "These mice also exhibit cognitive deficits, including impaired social interaction and repetitive behaviors and hippocampus-dependent spatial memory deficits, highlighting Cx3cr1’s broader role in cognitive function." (PMID 39792668, 2025). "A role of microglia is also suggested by the finding that knockout of the microglia-specific fractalkine receptor CX3CR1 increases LPS-induced tau phosphorylation, aggregation, neuroinflammation and cognitive impairment in an hTau mouse model of tauopathy." (PMID 38561809, 2024). "However, data from other transgenic mice lines (CX3CR1 (−/−, ±)) suggest that reduced neuron–microglial fractalkine signaling may be linked to reduced synaptic plasticity, reduced hippocampal neurogenesis and cognitive impairment." (PMID 38093257, 2023). "In contrast, in a cerebral ischemia model, CX3CL1/CX3CR1 downregulation significantly reversed cognitive deficits by inhibiting microglia activation and promoting oligodendrocyte progenitor cell maturation and myelin regeneration." (PMID 37234914, 2023). "This study identifies for the first time the role of CX3CR1 in high-altitude-induced cognitive impairment." (PMID 37234914, 2023). "On the other hand, long-term HFD feeding mice show reduced expression of both fractalkine and CX3CR1 in the hippocampus and amygdala, accompanied by defective synaptic plasticity and cognitive impairment." (PMID 36869375, 2023). "Lastly, it is worth mentioning that extensive evidence supports the role of CX3CL1/CX3CR1 axis disruption in neuronal damage leading to cognitive impairment and dementia in AD patients." (PMID 36233371, 2022). "Studies using animal models have also indicated a link between CX3CL1/CX3CR1 and severity of depressive behavior and cognitive impairment." (PMID 35782435, 2022). "Others noted that decreasing CX3CL1/CX3CR1 signaling activity exacerbated plaque-independent cognitive deficits in APP-overexpressing AD mouse models; deficiency in CX3CR1 was found to increase tau hyperphosphorylation and to increase neurodegeneration." (PMID 31822518, 2020). "Especially under acute plateau exposure, CX3CR1 inhibition may be an effective therapeutic approach, thus broadening the horizon for the treatment of cognitive impairment." (PMID 37234914, 2023). "Several studies have reported the protective effect of CX3CR1/L1; however, this is the first study to state that the regulation of CX3CR1/L1 can improve cognitive impairment after surgery via modulation of GABA expression, which is mediated by the regulation of astrocyte activation." (PMID 33858422, 2021). "Also, this is the first study to show that the regulation of CX3CR1/L1 can improve postoperative cognitive impairment via modulation of GABA expression, which is mediated by the regulation of astrocyte activation." (PMID 33858422, 2021). "This study further confirmed the potential therapeutic effects of regulating CX3CR1/L1 signaling to prevent cognitive impairment in POCD, via modulation of persistent pain and inflammatory response, as well as GABA signaling, by regulating astrocyte activation." (PMID 33858422, 2021). "In summary, inhibition of CX3CR1 signaling by injection of neutralizing Ab suppressed the increase in pro-inflammatory cytokines via inhibition of persistent pain that occurred after TF surgery; it also ameliorated cognitive impairment." (PMID 33858422, 2021). "Furthermore, both CX3CR1 and ST6GAL1 have been linked to cognitive impairment." (PMID 39290304, 2024).
Cognitive impairment (continued). "Indeed, a disrupted CX3CL1/CX3CR1 axis (microglial-neuron communication) is associated with increased IL1β protein levels, and the blockage of IL1-R1 was sufficient to reverse long-term potentiation (LTP) and cognitive impairments in CX3CR1 knockout mice." (PMID 32961703, 2020). "Indeed, hAPP-CX3CR1-/- mice as well as hTau-CX3CR1-/- mice showed increased expression of inflammatory factors, enhanced tau phosphorylation, and exacerbated neuronal dysfunction and cognitive deficits." (PMID 30319362, 2018). "In this study, we examined changes in CX3CR1 expression levels in the TF-induced POCD model and the potential therapeutic effect of CX3CL1 as a new treatment candidate for alleviating cognitive impairment by regulating inflammation." (PMID 33858422, 2021). "A third study examined the effects of CCI in mice missing one allele of CX3CR1 and found that the female mice, but not the male mice, showed significantly better symptoms post-injury, including less neurodegeneration, leukocyte infiltration and cognitive deficits." (PMID 30319362, 2018). "However, based on the complexity of the regulatory mechanism of cognitive impairment, it can be concluded that CX3CL1/CX3CR1 is only one of the factors affecting high-altitude-induced cognitive impairment." (PMID 37234914, 2023). "A negative correlation was seen between the number of CX3CR1-expressing NK cells and the severity of cognitive impairment." (PMID 36405736, 2022). "In a chronic model of inflammation, hTau mice lacking the fractalkine receptor (CX3CR1) exhibited not only significantly greater pathology but also a significantly earlier onset of pathology and cognitive impairments." (PMID 30744705, 2019). "Based on these data, we suggest that regulation of CX3CR1/L1 signaling by injection of neutralizing Ab after surgery affected the level of GABA expression and mechanical allodynia, which might consequently improve cognitive impairment." (PMID 33858422, 2021).